CD4 (CD4 molecule)
Diseases named in the same sentence as CD4 in open-access papers (continued):
Sharing a sentence is not in itself a finding about the gene and the disease.
tumor (continued). "Tumoral samples from B-NHL patients, including FL, DLBCL, MCL, MZL and CLL, present overexpression of TIGIT in CD4+ and CD8+ T-cells, which produce lower levels of proinflammatory cytokines as well as expression of the ligand CD155 in the TME." (PMID 33430146, 2021). "Regulatory T-cells (Tregs) represent a critical subset of CD4 T-cells, characterized by CD4 + CD25+ Forkhead box P3+ (FoxP3+) phenotype, able to control peripheral tolerance and responses to foreign and tumor antigens." (PMID 34640606, 2021). "There are also significant increases in the percentage of circulating monocytes (CD45+CD11b+Ly6Chi), CD4 T-cells (CD45+CD4+CD8−), and CD8 T-cells (CD45+CD8+CD4−) out of CD45+ cells in the tumour-bearing mice with E2V." (PMID 34511060, 2021). "Dendritic cells (DC) participate in the antitumor process due to their ability to cross-present antigens to CD4+ and CD8+ T cells for killing tumor cells." (PMID 34867821, 2021). "Whereas the percentages of tumor-infiltrating CD4+ and CD8+ T cells only slightly changed with tumor progression, most of the T cells expressed either one of the inhibitory receptors PD-1 and TIM-3 or both." (PMID 33408092, 2021). "At the endpoint (24–28 weeks old), even when tumors were large and necrotic, we found that both CD4+ and CD8+ tumor-infiltrating T cells still displayed an improved functional phenotype in KO tumors." (PMID 34283809, 2021). "Multiplex immunohistochemistry showed that PD-1H was detected in CD4 T cells, CD8 T cells, and CD68 macrophages of ESCC tumor tissues." (PMID 34950702, 2021). "Results showed that the expression of CXCL9 was negatively correlated to tumor purity, and positively correlated to the levels of immune cells, including B cells, CD8+T cells, CD4+T cells, macrophages, neutrophils, and dendritic cell." (PMID 33854600, 2021). "Through the processing and presentation of antigens on their cell surface, they can activate both CD4+ and CD8+ T cells and thus promote rejection of tumor cells." (PMID 34445275, 2021). "Through integration analysis, our findings show that DEirlncRNA pairs have a positive correlation with tumor-infiltrating immune cells such as B cells, neutrophils, and macrophages but are negatively correlated with CD8+ T cells, CD4+ T cells, and monocytes." (PMID 34923955, 2021). "Regulatory T cells (Tregs), which express the CD4, CD25 and FOXP3 phenotypes, are found in tumour microenvironments and induce immune tolerance as they downregulate CD4 helper and CD8 cytotoxic T cells." (PMID 34206956, 2021). "As tumor cells more readily express MHC-I molecules, DC play a pivotal role in the activation and priming of CD4+ T cells to initiate the CD4+ anti-tumor response." (PMID 34012451, 2021). "Poly6 treatment also significantly increased expression levels of CD44, indicative surface markers for activated T cells, on CD4+ and CD8+ T cells in the tumor and spleen." (PMID 33499256, 2021). "We selected the markers of the immune checkpoint molecule (PD1, PD-L1, and LAG-3) and immune cell (CD3, CD4, CD8, and Foxp3) as markers of the tumor microenvironment." (PMID 34484468, 2021). "Treatment with the anti-CD38 antibody in mice that are resistant to IC blockade therapy inhibits tumor growth, enhances effector CD8+ and CD4+ T-cell responses and reduces CD4+ Treg cells and MDSCs." (PMID 33467713, 2021). "We therefore highlight, for the first time, that the inhibition of TSP1 expression enhanced tumor infiltration by various T lymphocyte subpopulations, including not only CD8+ and CD4+ T cells but also Tregs." (PMID 34439212, 2021). "The formulation was proven to stimulate the maturation of DCs and consequently the expansion of both CD4+ and CD8+ OVA-specific T cells, which resulted in a strong T cell immunity against tumours." (PMID 34073106, 2021).
tumor (continued). "A better selection of starting biological product using either anti-CD3/CD28 bead activation for CD3+ cell selection or specific immunomagnetic CD4+ and CD8+ sorting will avoid bringing tumor cells into the production process." (PMID 33414517, 2021). "CCL2 and C-C motif chemokine ligand 17 (CCL17) support tumour growth by recruiting CD4+ Treg cells and macrophages, while VEGF and MMP-9 stimulate angiogenesis and tumour cells migration." (PMID 34769447, 2021). "Overall, EZH2 inhibition increased CD4+ and CD8+ tumor infiltration in mice and potentiate prostate cancer response to anti-PD-1 therapy." (PMID 34262562, 2021). "CD4+ and CD8+ αβ T-cells emerged as the primary effector cells of the anti-tumour immune response but their function in cancer patients is often compromised." (PMID 34960140, 2021). "Studies have shown that an infusion product formulated with defined CD4+ and CD8+ subsets in a 1:1 ratio enhances in vivo anti-tumor activity." (PMID 34172810, 2021). "At baseline, MPEs contain a lower frequency of CD4+ and CD4+ regulatory (Foxp3+) T cells compared to matched NSCLC tumor tissue, whereas CD8+ T cells were increased in the MPE compared to tumor samples." (PMID 33987104, 2021). "This suggested that GPX4 and AIFM2 played important roles in regulating tumor immunity by affecting the ferroptosis of B cell, CD8+ T cell, and CD4+ T cell in HNSC." (PMID 34722530, 2021). "For tumor immune cell infiltration, the results suggested that CDKN2A expression was positively related to CD8 T cells, NK activated cells and CD4 T activated cells but negatively related to memory resting CD4 T cells and resting CD4 T cells." (PMID 35004697, 2021). "Our data show that majority of the DMR’s in tumor infiltrating CD4+ T cells were concentrated between ~2Kb upstream and downstream to the TSS, implying that tumor influences epigenetic changes in tumor infiltrating helper T-cells." (PMID 34012510, 2021). "For CD4+ helper (Foxp3-) T cells and regulatory (Foxp3+) T cells, the expression of PD-1 and TIM-3 are similar between matched MPE and tumor tissue both pre- and post-chemotherapy." (PMID 33987104, 2021). "However, subsequent single-cell RNA sequencing of the LLC-OVA tumor-infiltrating TCRβ+ cell compartment revealed that Ccr8 expression was not restricted to ti-Tregs, but could also be found in populations of dysfunctional CD4+ and CD8+ T cells." (PMID 33589525, 2021). "Tumor antigen presentation by MHC class I and II molecules is critical to CD8+ and CD4+ T cell-mediated adaptive immune responses." (PMID 34452019, 2021). "While the majority of cancer immunotherapies focus on harnessing the anti-tumour CD8+ cytotoxic T cell response, the potential role of CD4+ ‘helper’ T cells has largely remained in the background." (PMID 32457487, 2021). "The adaptive immune cell assessment revealed very effective CD4+ and CD8+ T cell infiltration in both tumor types in MBTA-treated mice, with the highest-level changes observed in the CD8E/EM T cells." (PMID 34439097, 2021). "Analysis of T-cell spatial distribution revealed poor CD4+ and CD8+ cell infiltration within tumoural areas, where enrichment of CD4+/FOXP3+ was more prevalent." (PMID 33946676, 2021). "As IFNγ is secreted by macrophages and CD4+ and CD8+ T lymphocytes in the tumor microenvironment, it was conceivable that CD74 overexpression in solid tumors, and prognostic value, is simply a reflection of the level of immune infiltration." (PMID 34944801, 2021). "CD4+ and CD8+ T cells, NK cells, conventional type 1 dendritic cells (cDC1s) and cDC2s, NK cells, and neutrophils were all recruited to the tumor over the course of 6 days following a single dose of AIPV, and the CD8/Treg ratio shifted dramatically." (PMID 34818534, 2021).
tumor (continued). "The results showed that KIAA1429, HAMP, AQP9, CCL13, and CCL21 were significantly negatively correlated with tumor purity, and KIAA1429 was highly correlated with B cells, CD8 T cells, CD4 T cells, macrophages, neutrophils, and dendritic cells." (PMID 34422053, 2021). "Specific subsets of lymphocytes were also analysed (CD3, CD4, CD8, CD45R0, and FoxP3 cells) within different tumour locations (tumour center, invasive margin, and stroma)." (PMID 34940086, 2021). "At the same time, we found that the number of CD4+ and CD8+ T cells in tumor tissues increased significantly." (PMID 34295341, 2021). "This suggests that HLA-DRB1*07 carriers are likely to present tumour cell derived antigenic peptides, and that downregulation of HLA expression in HRS cells is required to overcome CD4+ T cell orchestrated anti-tumour responses." (PMID 34830986, 2021). "Both cryo-thermal Mφs and cryo-thermal DCs increased the level of granzyme B in CD4+ T cells compared to the tumor-bearing group, but DCs from cryo-thermal therapy with DFO treatment decreased the level of granzyme B in CD4+ T cells." (PMID 34209797, 2021). "Specifically, TCL6 was positively correlated with tumor infiltration with immune cells, including CD8+ and CD4+ T lymphocytes, neutrophils, B and DCs, as well as with the expression of PD-1, PD-L1, PD-L2 and CTLA-4 immune checkpoint molecules." (PMID 34943820, 2021). "Investigation of the TME in PC shows that immune cells with inhibitory phenotypes such as CD4+ forkhead box P3 (Foxp3+) and CD8+ FOXP3+ Tregs accumulate within the epithelial compartment the tumor margin." (PMID 34868907, 2021). "We found that in PRMT5 knockdown tumor microenvironment, the expression of IFN-γ and TNF-α in CD4+ T and CD8+ T cells were increased, and the expression of granzyme B in CD8+ T cells was also upregulated." (PMID 34522232, 2021). "DCs are key players in the generation of T cell anti-tumour immunity, as they mediate the processing of tumour antigens and their presentation to naïve CD8+ and CD4+ T cells in the draining lymph nodes." (PMID 34073106, 2021). "In this study, BEMPEG also inhibited primary tumor growth and metastatic relapse in the lungs and bone tissue after K7M3 primary tumor resection, with a concurrent increase in CD8+ and CD4+ T‐cell infiltration in the bone and lungs." (PMID 33152115, 2021). "In addition, T cells are the primary cell type in tumor immunity; among them, CD4+ subtypes could modulate the anti-tumor immunity via secreting cytokines, while CD8+ subtypes could conduct the secretion of specific inhibitory cytokines, including IFN-γ and TNF-α." (PMID 33435880, 2021). "At the same time, the expression patterns of ZC3H12B, T cell markers CD4 and CD8, M1 type markers CD14 and CD86, and M2 type markers CD163 and CD206 were also detected in mouse tumor tissues." (PMID 33718596, 2021). "In the tumor microenvironment (TME), CD4+ T cells can directly kill tumors and/or change the TME to promote anti-tumor immunity." (PMID 33708224, 2021). "In tumor‐bearing mice one‐week post‐treatment, let‐7b led to increased accumulation of CD8+ T cells (p < 0.001), increased effector‐memory CD4+ and CD8+ T cells (p < 0.001), and decreased naïve CD4+ and CD8+T cells (p < 0.001)." (PMID 34236760, 2021). "Tumor-infiltrating TC were stained with fluorescent Abs against the Treg-distinguishing markers CD4, CD25, CD127, and CD45RA51 and the CD4+ gate was “index sorted” as one cell per well in a plate format." (PMID 33602930, 2021). "Our data reiterate that CD4+ and CD8+ TILs comprise heterogenous populations, perform distinct roles, and affect unique pathways which dictate CRC tumor progression." (PMID 33916009, 2021). "DCs have a wide range of antigen presentations and are essential for the activation of both helper CD4+ and cytotoxic CD8+ T cells, especially for processing tumor antigens and priming anti-tumor immunity." (PMID 35250965, 2021).
tumor (continued). "The median of average cell numbers in CD3+, CD4+ and CD8+ T cells was 942.5, 153.1, and 111.2 /mm2 tumor area, respectively." (PMID 34758773, 2021). "CD4+FOXP3+ regulatory T cells (Tregs), a suppressive subset of T cells, can impair anti-tumor responses and reduce the efficacy of currently available immunotherapies." (PMID 34712661, 2021). "The proportion of proliferating stromal immune cells was positively correlated with the amount of tumour area in the sample (Spearman Rho, CD3+Ki67+ = 0.397, CD8+Ki67+ = 0.331, CD4+Ki67+ = 0.414, Foxp3+Ki67+ = 0.395, P < 0.001)." (PMID 33742063, 2021). "An increase was detected in the ratios of CD8+IFNγ+/CD4+FoxP3+ T cells and CD8+IFNγ+/CD11b+Ly6G+ cells in pHIFU + ICI-treated tumours relative to controls." (PMID 34229458, 2021). "TIMER2, which offers many existing algorithms for estimating tumor-infiltrating immune cell populations, showed a remarkable correlation between LEPROT expression and CD4+, CD8+, and regulatory T cells." (PMID 34804118, 2021). "It have been reported that DCs migrate into tumor-draining lymph nodes and prime CD8+ or CD4+ T cells to induce antitumor responses in mouse models, although their manipulation in cancer vaccination protocols has not reached a potent clinical impact." (PMID 33737571, 2021). "The anti-tumor effects of VTX-2337+ cetuximab were accompanied by increased splenic lymphoid DCs and IFNγ+ CD4+ and tumor-specific CD8+ T cells." (PMID 33452311, 2021). "Apart from the dominant effect of CD8+ T cells in enforcing dormancy, CD4+ T cells secrete IFN-γ, and the binding TNFR1 can induce tumor growth arrest and establish tumor dormancy in a mouse model of pancreatic cancer." (PMID 34831048, 2021). "Presentation of tumor antigens to CD8+ cytotoxic T cells and CD4+ helper T cells by HLA class I and class II molecules, respectively, is a key component of this process." (PMID 34422644, 2021). "Consistent with the enhancement of expression of IFN-γ, subcutaneously administered PLP significantly increased the infiltration of CD4+ IFN-γ+ and CD8+ IFN-γ+ T cells to the tumor sites." (PMID 34504423, 2021). "It is known that cytotoxic CD4+ GZMB+ T cells recognize tumor antigens in an MHC class-II context and lyse tumor cells directly, which can be hampered by tumor infiltrating Treg cells." (PMID 34631551, 2021). "There was a strong positive correlation between the infiltration of CD20+ B cells, cytotoxic CD4+ and CD8+ T cells, regulatory FOXP3+ T cells, and CD68+ and CD163+ macrophages in both stroma and tumor nests." (PMID 33494389, 2021). "Tregs inhibit cell-mediated immunity carried out by CD4+ and CD8+ T cells, thus enabling tumours to evade immunity." (PMID 34943783, 2021). "This was effective both in vitro and CD11b +, promoted the DC maturation and upregulated T cell proliferation, also decreasing the apoptosis of CD4+ T and CD8+T cells with increased tumor-specific cytotoxicity." (PMID 34452128, 2021). "In response to cancer, CD4+ T cells provide help in the priming of tumor-specific CD8+ T cells, thus permitting the differentiation and expansion of tumor antigen-specific CTLs50." (PMID 33986437, 2021). "As shown in the results of the current cohort, some subtypes of TILs present in the residual tumor such as CD3, CD8, and CD4, as well as CD4/FOXP3 and CD8/FOXP3 ratios, influenced survival outcomes." (PMID 34858800, 2021). "We reveal that PTEN mRNA expression is significantly positively correlated with CD4/CD8A gene expression and T cells infiltration especially T helpers cells, central memory T cell and effector memory T cells in multiples tumor types." (PMID 33874915, 2021). "By blocking this signal through Sirpα binding, the surface of the tumor cells is coated with the drug, allowing the CD40L side to bind to CD40 on APCs, which will lead to enhanced antigen presentation to CD8+ and CD4+ T lymphocytes and tumor cell phagocytosis." (PMID 35070956, 2021).
tumor (continued). "In tumor bearing mouse models, this action of CTLA-4 blockade translates into the expansion of both CD4 + and CD8 + effector T cells in the tumor microenvironment (TME)." (PMID 33602280, 2021). "Through flow cytometry analysis, we found that Ccng2−/− mice exhibited an increased frequency of tumor-infiltrating Tregs and decreased frequency of IFN-γ + CD4 + T cells and IFN-γ + CD8 + T cells." (PMID 34452627, 2021). "We first measured the expression level of IL-18 receptors (IL-18Rα) on the CD3+ CD4+ and CD3+ CD8+ subsets ex vivo from cell suspensions obtained just after mechanical dissociation of fresh tumor fragments (n = 19; 11 MSS and 8 MSI CRCs)." (PMID 33430344, 2021). "The immunosuppressive effects of RT include recruitment of specific immune subsets and polarization of immune subsets into a pro-tumor phenotype, such as Tregs, MDSCs, TH2 cells, TH2-skewed CD4+T cells, and M2-TAMs." (PMID 34247198, 2021). "To compare the distribution of CD4+ and CD8+ T-cell clones within the tumor and periphery, we used the Morisita–Horn index, which calculates clonal overlap between two populations." (PMID 33594075, 2021). "The increase in the ratio of CD8:CD4, CD25 T cells predicts more active/anti-tumor cytotoxic CD8 T cells, and qPCR of whole lung lysates showed an increase in the expression of INFγ in all groups." (PMID 34638488, 2021). "In contrast, the tumor tissue after a treatment with the anti-PD1 antibody showed strong stainings for CD3-, CD4-, and CD8-positive cells (third column) and unaltered strong CD204 positivity (third column)." (PMID 34063518, 2021). "During an immune response, PD-1 is transiently expressed on CD4+ and CD8+ T cells, B cells, natural killer (NK) cells, monocytes, dendritic cells (DCs), and tumor-infiltrating lymphocytes (TILs)." (PMID 34571982, 2021). "In the TCGA cohort, CHIM samples had higher levels of anti-tumor cells, including CD8+ T cells, M1 macrophages, and CD4+ activated memory T cells, than the other two subtypes, whereas they had lower frequencies of M0 macrophage and CD4+ resting memory T cells." (PMID 34177954, 2021). "Regulatory T cells, which cooperate in tumour development and growth, also clearly responded to ITPP treatment, as the proportion of CD45+CD4+CD25+FoxP3+ Treg cells was significantly decreased in B16F10 Luc tumours when treated with ITPP." (PMID 33624446, 2021). "Strikingly, we observed an increase in quiescent DN cells (DN(Q)) and a slight decrease in SP CD4 and CD8 cells based on thymocyte-specific marker gene expression in ALK tumor samples." (PMID 33310759, 2021). "Tumour-infiltrating immune markers (CD3, CD4, CD8, CD20, CD56, CD68, PD-1, PD-L1) were assessed by immunohistochemistry." (PMID 33087896, 2021). "The combination of 2 mAbs significantly increased CD8+ and CD4+ cells and decreased immunosuppressive CD4+FoxP3+ Tregs and CD11b+Gr-1+ Myeloid Suppressor Cells (MDSC) at tumor sites." (PMID 34267616, 2021). "We also analyzed the abundance of total CD3+ T cells and/or CD4+ and CD8+ T cell subsets in the peripheral blood and dissociated tumor tissues by flow cytometry." (PMID 34054817, 2021). "The TIL consists of all the lymphocytic cell populations, like CD4+ helper T cells (Th1), CTL, B cells and NK cells, that have surrounded the tumor tissue, and the presence of these immune cells are considered abundant in TNBC and HER2+ tumor patients." (PMID 34829916, 2021). "In immune-competent BALB/c mice, the in vivo tumor growth of 4T1-CXCL13 was significantly inhibited and even completely eradicated, accompanied with increased infiltrations of CD4+, CD8+ T lymphocytes, and CD11b+CD11c+ DCs." (PMID 35693216, 2021). "The results of blockade of CD4+ T cells and CD8+ T cells showed that both anti-CD4 and anti-CD8 completely abolished the anti-tumor effects of AAGL." (PMID 33710817, 2021).